CFB (complement factor B)
Diseases named in the same sentence as CFB in open-access papers (continued):
Sharing a sentence is not in itself a finding about the gene and the disease.
Obesity (5 papers, 2017 to 2025). Accumulation of substantial excess body fat. "The following seven proteins are present in higher amounts in the Obesity group compared with the Control group: hemopexin—HPX, complement factor B—CFB, complement C3—C3, kininogen-1—KNG1, vitronectin—VTN, pigment epithelium-derived factor—SERPINF1 and beta-Ala-His dipeptidase—CNDP1." (PMID 41441338, 2025). "Of those changes identified in the tumor microenvironments of ccRCC subjects with obesity versus non-obese counterparts, those with the largest fold changes were CD36 (+2.514, P = 0.045), IDO1 (+2.46, P = 0.012), CFB (+2.0, P = 0.041), CD7 (-4.66, P = 0.046), and CCL21 (-5.28, P = 0.0097)." (PMID 32469992, 2020).
pancreatic cancer (5 papers, 2020 to 2023). "In pancreatic cancer, the accumulation of CFB is associated with immune evasion, making it a potential target for immunotherapy." (PMID 37628784, 2023). "Noteworthy, CFB is a prognostic preoperative marker in pancreatic carcinoma which outperformed CA19–9 and CEA." (PMID 34670568, 2021). "An increased level of CFB has very high sensitivity and specificity for the diagnosis of pancreatic cancer, and its false-positive rate is lower than that of the common tumor marker CA19-9." (PMID 33193731, 2020). "Moreover, other studies have found that plasma levels of CFB in pancreatic cancer patients were two-fold higher than those of normal volunteers." (PMID 37325058, 2023). "Studies have shown that CFB may be a new tumor marker for the diagnosis of pancreatic cancer." (PMID 33193731, 2020).
C3 glomerulopathy (4 papers, 2019 to 2024). "CFB variants have been described in patients with aHUS, in C3 glomerulopathy and in a few patients with immune-complex associated MPGN but not all of them exhibit gain-of-function." (PMID 34177949, 2021). "In addition to aHUS, CFB mutations and rare variants have also been demonstrated in C3 glomerulopathy and immune complex-associated membranoproliferative glomerulonephritis (MPGN)." (PMID 34177949, 2021). "Hyperactivation of the alternative complement pathway with involvement of CFB results in the development of C3 glomerulopathy, which leads to accumulation of the C3 component and glomerular injury." (PMID 39896931, 2024). "In TMA, especially in aHUS, and C3 glomerulopathy, genetic sequencing studies have contributed to the identification of genetic variants involved in the complement pathways, such as: CFH, CFI, MCP/CD46, complement factor B (CFB), thrombomodulin (THBD), C3 and others." (PMID 39780910, 2024).
diabetic nephropathy (4 papers, 2021 to 2024). "We found that in patients with diabetic nephropathy, the staining of Bb, CFB, C3a, C5a, and C5b-9 was markedly elevated in renal tubulointerstitium." (PMID 36546481, 2022). "The role and mechanisms for upregulating complement factor B (CFB) expression in podocyte dysfunction in diabetic kidney disease (DKD) are not fully understood." (PMID 34622800, 2021). "Furthermore, in diabetic nephropathy, podocyte injury has been reported to involve other serine proteases, such as factor X (FX) and complement factor B." (PMID 37958726, 2023). "In addition, our recent study found that in patients with diabetic nephropathy (DN), both circulating and urinary levels of CFB were significantly higher than in healthy controls (HCs), and urinary levels of CFB correlated with the severity of DN." (PMID 36546481, 2022).
endometrial cancer (4 papers, 2016 to 2024). Primary or metastatic malignant neoplasm involving the endometrium (mucous membrane that lines the endometrial cavity). "Particularly, expression of TFAP2A, MMP12, TOP2A, ASPM and CFB were higher in endometrial cancer relative to normal tissues." (PMID 32555395, 2020).
Hypertension (4 papers, 2017 to 2025). The presence of chronic increased pressure in the systemic arterial system. "At the human CFB locus, 3 single-nucleotide polymorphisms are significantly associated with visceral adiposity, hypertension, and CFB gene expression." (PMID 28739975, 2017). "In silico analysis of the human CFB locus revealed 2 cis-regulated expression quantitative trait loci for CFB expression significantly associated with visceral fat, circulating triglycerides and hypertension in genome-wide association studies." (PMID 28739975, 2017). "One patient with a severe predisposition (CFB pathogenic variant) had a normal delivery, whereas three patients with no identified pathogenic variants had severe bleeding complications, hypertension or pre-eclampsia, and consequently more severe clinical presentations." (PMID 33407224, 2021). "SNPs in human CFB are associated both with hypertension and visceral adiposity and with CFB gene expression, suggesting that genetic variation in CFB may, in part, explain the genetic associations at the human CFB locus." (PMID 28739975, 2017). "Further, 1 SNP, rs805303, was significantly positively correlated with systolic and diastolic blood pressure, and hypertension, as well as with increased CFB expression." (PMID 28739975, 2017). "Work in a rat model of spontaneous hypertension (exhibits hypertension, insulin resistance and dyslipidemia, features of metabolic syndrome) showed that knocking out the CFB gene improved glucose tolerance and insulin sensitivity, with redistribution of visceral to subcutaneous fat." (PMID 36377667, 2023).
lung adenocarcinoma (4 papers, 2021 to 2025). A carcinoma that arises from the lung and is characterized by the presence of malignant glandular epithelial cells. "While our findings align with these findings, the role of CFB remains controversial, with studies reporting anti-tumor effects in lung adenocarcinoma, whereas its expression is associated with poor prognosis in prostate cancer." (PMID 40283026, 2025). "A low CFB expression has been associated with a poor overall survival and a more aggressive disease in different solid tumors, including lung adenocarcinoma and pancreatic ductal adenocarcinoma." (PMID 35328227, 2022). "Additionally, the expression of CFB is downregulated in clinical samples of lung adenocarcinoma (LUAD), while its overexpression can inhibit tumor growth, cell proliferation, and migration, and promote cell apoptosis and cell cycle arrest." (PMID 40496561, 2025).
melanoma (4 papers, 2015 to 2023). A malignant, usually aggressive tumor composed of atypical, neoplastic melanocytes. "Although previous studies support a negative role for CFB in squamous cell carcinoma mouse models, and C7 in patients with glioma, the role of these complement factors in melanoma disease recurrence needs to be further elucidated." (PMID 37089863, 2023). "The complement component (C7), complement factor B (CFB), and A1BG showed a significant increased expression in patients with stage IV melanoma (P = 0.0070, P = 0.0107, P = 0.0371, respectively) and nonresponding patients with a recurrence (P = 0.0302, P = 0.0400, P = 0.0208, respectively)." (PMID 37089863, 2023).
pancreatic ductal adenocarcinoma (4 papers, 2021 to 2023). An infiltrating adenocarcinoma that arises from the epithelial cells of the pancreas. "Furthermore, complement factor B was shown to be prevalent in the microenvironment of pancreatic ductal adenocarcinoma and was associated with poor patient survival, potentially explained by complement factor B’s function in promoting cell proliferation." (PMID 38081362, 2023). "To validate these clinical data in an independent cohort, we evaluated CFB mRNA expression in a publicly available pancreatic ductal adenocarcinoma dataset of The Cancer Genome Atlas (TCGA-PAAD)." (PMID 34075561, 2021).
thyroid carcinoma (4 papers, 2022 to 2025). "Plasma complement factor B expression was linearly associated with macrophage M1 cells in the tumor microenvironment of thyroid carcinoma." (PMID 36457341, 2022). "High CFB expression has previously been implicated in worse survival in thyroid carcinoma and LUAD." (PMID 40327401, 2025). "Higher expression of plasma complement factor B (CFB) in thyroid carcinoma is correlated with a better survival." (PMID 37158852, 2023).
type 2 diabetes (4 papers, 2013 to 2021). "In summary, this study first revealed that CFH and CFB polymorphisms are associated with the development of DR, as well as with delayed progression to DR in type 2 diabetes." (PMID 23864767, 2013). "CFB is a crucial factor for activating the alternative complement pathway, which is elevated in adipose tissue and serum from patients with type 2 diabetes, but the correlation between CFB and DN has not been illustrated yet." (PMID 34124269, 2021).
uveitis (4 papers, 2017 to 2025). An inflammatory process affecting a part of or the entire uvea. "Elevated levels of C3a, C3c, and CFB proteins have also been reported in the aqueous humor of uveitis patients." (PMID 38187376, 2023). "Of these, variants in CFH, CFB and CFI involved in the alternative complement pathway, were identified as genetic risk factors for uveitis and specific subtypes." (PMID 28408754, 2017).
viral infection (4 papers, 2012 to 2022). "Further, patients deficient in complement regulatory proteins, such as factor H (CFH) and factor B (CFB), are predisposed to bacterial and viral infections." (PMID 35764881, 2022). "The patient with a CFB mutation (patient 8) relapsed > 1 year after achieving remission, precipitated by both vaccination and viral infection, and required an additional two doses of eculizumab." (PMID 26559391, 2016).
chronic hepatitis B (3 papers, 2020 to 2022). "CFB is associated with HBV related HCC and is considered as a potential predictor of response to PegIFNα therapy in patients with chronic hepatitis B." (PMID 33495404, 2021).
colitis (3 papers, 2019 to 2025). Inflammation of the colon. "Of note, DSS-induced colitis mouse model was constructed to demonstrate that the expression of key anoikis genes, namely H2-DMa, CX3CL1, and CFB were significantly upregulated, while PDK4 was evidently downregulated." (PMID 40115777, 2025).
glaucoma (3 papers, 2017 to 2024). Increased pressure in the eyeball due to obstruction of the outflow of aqueous humor. "Furthermore, increased expression of alternative pathway-associated CFB was also detected in the retina of IOP-dependent and IOP-independent models of glaucoma." (PMID 38396986, 2024). "They found a significant increase in the expression of complement proteins (C1R, C2, C4A/C4B, C5, C6, C8A, C9, CFB, CFI, and VTN) in glaucoma patients as compared to the control cataract patients." (PMID 38396986, 2024).
Insulin resistance (3 papers, 2017 to 2020). Increased resistance towards insulin, that is, diminished effectiveness of insulin in reducing blood glucose levels. "protein C receptor, endothelial (EPCR) (PROCR), C1R, CFI, PLAT, C4BPB, and CFB are novel biomarkers for the development of insulin resistance." (PMID 30678306, 2019).
lupus nephritis (3 papers, 2024 to 2025). Glomerulonephritis in the context of systemic lupus erythematosus. "Studies have shown that CFB plays a crucial role in Crohn’s disease, RA, and lupus nephritis, suggesting that CFB may drive the inflammatory process in AS." (PMID 40002719, 2025).
metabolic syndrome (3 papers, 2017 to 2023). A cluster of metabolic risk factors for CARDIOVASCULAR DISEASES and TYPE 2 DIABETES MELLITUS. "Together, these data demonstrate a key role for CFB in the development of spontaneously hypertensive rat metabolic syndrome phenotypes and of related traits in humans and indicate the potential for CFB as a novel target for treatment of cardiometabolic disease." (PMID 28739975, 2017).
myocardial infarction (3 papers, 2014 to 2022). Gross necrosis of the myocardium, as a result of interruption of the blood supply to the area, as in coronary thrombosis. "HA-CaMKIIN targeted to cytoplasmic membranes acts outside the nucleus to mediate induction of complement factor B following myocardial infarct (Singh etal., 2009)." (PMID 24600394, 2014). "In a post-myocardial infarction hypertrophic model, CaMK II activation was found to promote expression of pro-inflammatory gene complement factor B (CFB) through the NF-κB pathway in both cardiomyocytes and mice, subsequently inducing cell membrane injury in cardiomyocytes." (PMID 33324685, 2020). "Furthermore, myocardial injury and inflammation after myocardial infarction are improved in mice with knockout CFB or CaMKII inhibition." (PMID 33324685, 2020).
paroxysmal nocturnal hemoglobinuria (3 papers, 2024 to 2025). Paroxysmal nocturnal hemoglobinuria (PNH) is an acquired clonal hematopoietic stem cell disorder characterized by corpuscular hemolytic anemia, bone marrow failure and frequent thrombotic events. "Iptacopan (FabhaltaTM), a complement factor B inhibitor, is approved for paroxysmal nocturnal hemoglobinuria." (PMID 38338330, 2024). "Iptacopan (FABHALTA®) is an oral complement Factor B inhibitor, which was approved on 5 December 2023 in the United States for the treatment of paroxysmal nocturnal hemoglobinuria (PNH) in adults." (PMID 40565360, 2025).
preeclampsia (3 papers, 2020 to 2025). Preeclampsia is a hypertensive disorder of pregnancy that is characterized by new-onset hypertension with proteinuria presenting after 20 weeks of gestation, and depending on mild or severe forms may initially present with severe headache, visual disturbances, and hyperreflexia. "These patients have higher complement mutation frequency, including rare germline mutations in the alternative CS pathway (CFHR1, CFHR3, CFI, CFB, and CD46) than women with preeclampsia, having similar rates of variants as the control population." (PMID 40904461, 2025). "Furthermore, the investigation identified a number of genetic variants in the genes of ADAMTS13, C3, CFH, CFB, thrombomodulin, MBL2, and MASP2 that were significantly linked with the occurrence of preeclampsia, according to the results of analyses A and B." (PMID 38673014, 2024). "Dysregulation of CFB has been suggested in pregnant women with preeclampsia." (PMID 33791032, 2020).
prostate carcinoma (3 papers, 2020 to 2025). A carcinoma that arises from epithelial cells of the prostate gland. "Among them, complement factor B gene (CFB) was predicted to be the most related gene in prostate cancer." (PMID 31929112, 2020). "However, there are few studies on the specific mechanism of CFB gene in prostate cancer." (PMID 31929112, 2020). "Interestingly, three components of the complement system, namely C3, C1R, and CFB, also showed a significant upregulation after interaction with the metastatic cell line MDA-MB231 and two of them (C3 and C1R) could be validated in the prostate cancer model." (PMID 31963450, 2020).
schizophrenia (3 papers, 2019 to 2025). A major psychotic disorder characterized by abnormalities in the perception or expression of reality. "We also probed the four complement genes located within the MHC region (i.e. C2, C4A, C4B and CFB) via schizophrenia PRS restricted to SNPs within each of them." (PMID 38649377, 2024).
staphylococcus aureus infection (3 papers, 2019 to 2023). An infectious process in which the bacteria Staphylococcus aureus is present. "In the early stage of infection, MASP1, MBL2, CFB, loc396877, loc100627396 linked complement and coagulation cascades with Staphylococcus aureus infection pathway, and C7, loc100736136 linked the Staphylococcus aureus infection with the prion disease pathway." (PMID 32632500, 2020).
acute kidney injury (2 papers, 2021 to 2022). Sudden and sustained deterioration of the kidney function characterized by decreased glomerular filtration rate, increased serum creatinine or oliguria. "The patient was later found to harbor a pathogenic variant in the CFB gene (C.1598A>G), and was diagnosed with aHUS and acute kidney injury." (PMID 33725982, 2021). "We report an adult with life-threatening anemia, thrombocytopenia, nervous system abnormalities, and acute kidney injury, who harbored a pathogenic variant in the CFB gene (C.1598A>G)." (PMID 33725982, 2021). "A study conducted in mice with septic shock indicated that the absence of CFB conferred a protective effect, with better survival and cardiac function and less markedly attenuated acute kidney injury." (PMID 36459524, 2022).
Arthritis (2 papers, 2016 to 2019). Inflammation of a joint. "Considering these facts, it is then logical to attribute the reduced CFB levels observed in the CSF of our arthritis patients to the reduced TNFα levels induced by the infliximab treatment." (PMID 30770760, 2019). "For example, complement factor B is essential for complement activation via the alternate pathway and so plays an important role in inflammatory conditions such as arthritis and muscle inflammation." (PMID 27160764, 2016). "Several immune-related proteins in the CSF of arthritis patients decreased during TNF blockade, including FGG and CFB that both correlated strongly with systemic inflammation." (PMID 30770760, 2019).
coronary heart disease (2 papers, 2017 to 2022). "Elevated, circulating complement factor B (CFB) increases the risk of endothelial dysfunction, which may lead to coronary heart disease." (PMID 34269526, 2022). "One SNP, rs76846904, close to the HLA-DRB5 gene, is highly correlated with CFB gene expression in subcutaneous adipose tissue (effect size, 0.78; P=0.000015) and within 100 kb of GWAS hits for visceral adiposity, serum cholesterol, and coronary heart disease." (PMID 28739975, 2017).
epidermoid carcinoma (2 papers, 2015 to 2023). "Moreover, CFB knockdown decreased both the migration in the skin-derived epidermoid carcinoma (A431) cell line and chemotaxis in human macrophages." (PMID 26540631, 2015). "The CFB knockdown in the skin-derived epidermoid carcinoma (A431) cells decreased the ability of the cells to migrate and the chemotaxis of human macrophages, which suggests that, in addition to a higher expression in OSCC tissues and saliva, CFB might mediate these events in carcinomas." (PMID 26540631, 2015).
hepatocellular carcinoma (2 papers, 2021 to 2024). A malignant tumor that arises from hepatocytes. "CFB promote migration and proliferation of Cutaneous Squamous Cell Carcinoma47, and overexpression of TMSB10 relate with hepatocellular carcinoma and renal cell carcinoma." (PMID 33712694, 2021).
influenza (2 papers, 2019 to 2021). An acute viral infection of the respiratory tract, occurring in isolated cases, in epidemics, or in pandemics; it is caused by serologically different strains of viruses (influenzaviruses) designated A, B, and C, has a 3-day incubation period, and usually lasts for 3 to 10 days. "These selected proteins, such as plasma protease C1 inhibitor, hemopexin, transferrin, complement factor B and complement C3, have been identified as candidate biomarkers of acute respiratory virus infection or exhibited obvious fold changes during influenza infection." (PMID 34867309, 2021).
liver cancer (2 papers, 2021 to 2025). An epithelial or non-epithelial malignant neoplasm that arises from the liver. "Kaplan–Meier analysis subsequently showed that C2orf27A and IGF2R were negatively correlated with the survival time of liver cancer patients, whereas CFB and PON1 were associated with favorable survival times." (PMID 33495404, 2021). "Antigenicity, molecular weight, subcellular localization and expression site predictions were used to shortlist liver cancer associated proteins including AMBP, CFB, CDHR5, VTN, APOBR, AFP, SERPINA1 and APOE." (PMID 39752339, 2025). "Among the four genes, C2orf27A and IGF2R were found to be positively correlated and CFB and PON1 were negatively correlated with the stage and tumor grade of liver cancer." (PMID 33495404, 2021).